MIR3688-1 (microRNA 3688-1)
Synonyms: hsa-mir-3688; hsa-mir-3688-1; MIR3688; mir-3688-1
Gene: MicroRNA gene on chromosome 4 (159,128,802 to 159,128,894, reverse strand). Ensembl gene ENSG00000264105.
Homologues: Orthologues: chimpanzee MIR3688-1 (100% identical).